Y_RNA (Y RNA )
Gene: Miscellaneous RNA gene on chromosome 5 (57,169,108 to 57,169,209, reverse strand). Ensembl gene ENSG00000207293.
Homologues: Orthologues: chimpanzee Y_RNA (100% identical), macaque Y_RNA (93% identical). Paralogues in human: Y_RNA (91% identical), RNY3 (90% identical), Y_RNA (90% identical), Y_RNA (89% identical), Y_RNA (88% identical), RNY3P1 (87% identical), Y_RNA (87% identical), Y_RNA (86% identical), Y_RNA (85% identical), RNY3P14 (84% identical), Y_RNA (84% identical), RNY3P11 (83% identical), and 98 more.